RELB (RELB proto-oncogene, NF-kB subunit)
Diseases named in the same sentence as RELB in open-access papers (continued):
Sharing a sentence is not in itself a finding about the gene and the disease.
tumor (continued). "Consequently, the nuclear localisation of RelB and p52 may evoke a normal transient activation, but may also reflect a cellular response to the tumour environment or a transitional state towards transformation." (PMID 16205698, 2005). "Among the NF-κB protein family members, including RelA, RelB, c-Rel, p50, and p52, p50 (NFKB1) has been identified as a significant tumor-promoting factor in cancer proliferation and metastasis, correlating with poor patient survival 33,34." (PMID 41041071, 2025). "Targeting intracellular PD-L1 has been shown to promote antitumor immune responses in some mouse tumor models, and nuclear PD-L1 upregulates several genes involved in immunosuppression, including PDCD1LG2, BIRC3, RELB, and VSIR." (PMID 39996786, 2025). "Further, expression levels of TF regulators in the NF-κB family (NFKB1, NFKB2, RELA, RELB) were highest in TS3 cluster, reinforcing the notion that NF-κB pathway activation within the tumor epithelium drives TS3." (PMID 39289380, 2024). "RELB, NFKB1, BCL3, and FOXO3, found in NEAT1+ tumor cells, were closely related to the CSCs phenotype." (PMID 37430270, 2023). "RelB but not RelA, was significantly upregulated in EEC, and silencing RelB in EEC cell lines affected colony formation, tumor growth in vivo and cell cycle progression." (PMID 31443240, 2019). "As expected, we found the activation of the TNF‐α/NF‐κB axis, and the knockdown of TNFR1, RelA, RelB, c‐Rel, and CUL4B showed similar effects on the proliferation, invasion, colony formation, and the in vivo tumor forming ability of cells." (PMID 29377600, 2018). "The expression levels of RelB in DCs + HCC (imDCs and mDCs) were markedly inhibited by tumor cells (*P < 0.05 or **P < 0.01)." (PMID 24410930, 2014). "The results showed that the gene transcription activity and energy states of DCs were suppressed by tumor cells, moreover, the absorption intensities of FTIR at given wave number were closely correlated with the expression levels of RelB." (PMID 24410930, 2014). "RelB expression varied widely among tumor cells from four different patients, with BT25 cells expressing the highest levels of RelB, comparable to U87 cells." (PMID 23451236, 2013). "Two transcription factors of this family present in our array, NFκB2 and RELB, showed over-expression in ESR1-negative BRCA1 tumours with fold changes relative to ESR1-positive tumours ranging from 3.7 to 4.1, respectively (two-tailed t-test P-values <0.05." (PMID 19826428, 2009). "Nevertheless, the limited tumor burden in thymus and lymph nodes of terminally ill TEL-JAK2;Tcra−/−;Relb−/− and TEL-JAK2;Tcra−/−→Tcra−/−;Relb−/− mice suggests that the RelB-dependent thymic microenvironment favors the expansion of transformed leukemic cells." (PMID 18596915, 2008). "Additionally, we found experimentally that miR-335-5p displayed tumor-suppressive properties in EOC cell lines, was regulated by both RELA and RELB, and, by mimicking its expression, suppressed TIC viability." (PMID 37175530, 2023). "Furthermore, quantitative reverse transcriptase polymerase chain reaction (qRT‐PCR) analyses confirmed the enhanced expression of RelB and NF‐κB2 in cytotoxin‐induced NDC‐cancer cells and NDC‐derived metastatic tumor tissues." (PMID 36739602, 2023). "Three weeks after the injection, metastatic lung tumours were detected in the control group, but not in the groups injected with RelB-KO tumour cells irrespective of PD-L1 expression in the cells, thus indicating that RelB is critical for PCa metastasis." (PMID 35177112, 2022). "Altogether, the Myd88L252P tumor signature highlights proliferation as well as canonical NF-κB p65/RelA activation (but not RelB), which is in agreement with the known fact that MYD88 activates the classical NF-κB pathway." (PMID 34017329, 2021). "Additionally, transcriptional activity of RelB/p52 can cooperate with genome stability enzymes, such as APOBECs and the TERT catalytic subunit of telomerase, to fuel tumor growth." (PMID 34292968, 2021).
tumor (continued). "The mRNA levels of RelB and NF-κB2 were significantly upregulated in HCC tissues compared to normal liver tissues in subgroup analyses based on patient's race, gender, age, weight, tumor grade, cancer stage, and nodal metastasis status." (PMID 32879628, 2020). "Interestingly, most deregulated genes, such as IL6, RelB, RelA, Plac8, ITGA5, CXCL12 and FN1, among other cytokines and growth factors, have been involved in tumor growth and progression." (PMID 32848147, 2020). "The present study has not merely observed RelB enhancing tumor growth, but more importantly discovered RelB enhancing the EMT process." (PMID 32807176, 2020). "For example, through a methyltransferase-independent mechanism, EZH2 induces transcriptional activation of RelB, a noncanonical NF-kB factor, to sustain tumor phenotypes in triple-negative breast cancer (TNBC)." (PMID 33327550, 2020). "On the contrary, NF-κB2 and RelB were observed in both compartments in only 10% of tumor-adjacent non-neoplastic tissues." (PMID 31586084, 2019). "It remains to be established whether both RelB and YY1 affect tumor generation or progression, but the later seems to be more likely based on our data." (PMID 31142741, 2019). "Although all studied proteins were overexpressed in NSCLC (P < 0.001 for all), only RelB mRNA levels were strongly increased in cancerous specimens compared to tumor-adjacent non-neoplastic tissues (P = 0.009)." (PMID 31586084, 2019). "The cytoplasmic expression of RelB correlates with tumour stage, and the nuclear expression of RelB detected by immunohistochemistry (IHC) in tissue samples from NSCLC patients differs between tumours and non-neoplastic tissues." (PMID 29983639, 2018). "Here, we determine that non-canonical IKKα-RelB pathway activation of KRAS-mutant tumor cells mediates MPE development and this is fueled by host-provided interleukin IL-1β." (PMID 29445180, 2018). "The results showed significantly enhanced expression of RelB, but not RelA, in EC tumor cell specimens." (PMID 27711077, 2016). "These genes included tumor markers (MUC16), genes that control tumor migration (MYL9), metastasis (CEACAM6, VEGFC, CX3CL1, CST1, CCL5, S100A9, IGF1, NOTCH3), cell adhesion (FN1, CEACAM1), and inflammation (TRAF2, NF-κB2 and RelB)." (PMID 26090868, 2015). "To assess the impact of RelB on the tumorigenicity of 22Rv1 cells in vivo, we performed subcutaneous injections of 22Rv1-RelB clones or 22Rv1-GFP cells into SCID mice and monitored the rate of tumor growth." (PMID 25788857, 2014). "The newly identified role of RelB as an important oncogenic driver of mesenchymal glioma provides a rationale for targeting the noncanonical NF-κB signaling pathway in high RelB-expressing tumors or tumor subtypes." (PMID 23451236, 2013). "Furthermore, upon treating various types of tumour cell lines with FOXO1 inhibitors, we observed not only the upregulation of VEGFC, PD‐L1 and CCL4 but also varying degrees of increase in MOMP‐related molecules (such as BAX, BAK1, CASP3, STING, IRF3 and RELB)." (PMID 38899748, 2024). "Furthermore, non-canonical NF-κB member RelB signaling was found to be elevated in endometrioid adenocarcinomas and connected to tumor initiation and tumor growth in vivo." (PMID 35328833, 2022). "In addition to the classical activation of RelA/NF-κB, more attention should be paid to the noncanonical RelB/NF-κB pathway in specific tumor types." (PMID 27711077, 2016). "Interestingly, tumor and stroma RelB expression were identified as positive and negative predictors of nodal involvement, respectively." (PMID 26147201, 2015). "Our results suggest that inhibition of the noncanonical RelB pathway will target cancer cell subtypes within a tumor that may be unresponsive to RelA inhibition and, consequently, may be part of a more effective treatment strategy for mesenchymal glioma." (PMID 23451236, 2013).
tumor (continued). "To evaluate whether knocking down RelA, RelB, and c‐Rel results in similar suppressive effects in vivo, we injected nude mice with RelA, RelB, c‐Rel, or control shRNA‐transduced U2OS cells and monitored the tumorigenesis for 30 days by measuring tumor volumes at 5‐day intervals." (PMID 29377600, 2018). "The immaturity of CD1a+ DCs within the tumour tissue was further demonstrated by the absence of maturity markers, such as DC-LAMP, CD40, or RelB expression, as assessed by serial analyses in confocal microscopy of double fluorescence-stained sections." (PMID 20969772, 2010). "RELB is part of the non-canonical NF- κB pathway, which was recently described to be “generating and maintaining CD8+ T cell memory” and could therefore be important for long-lasting tumor control." (PMID 40989699, 2025).
cancer (82 papers, 2005 to 2025). A tumor composed of atypical neoplastic, often pleomorphic cells that invade other tissues. "The complex is primarily composed of five members, including p50, p52, p65, c-Rel, and RelB, and dysregulation of this complex results in cancer and immune-associated diseases." (PMID 38612387, 2024). "Meanwhile, RelB expression was associated with TMB in 5 types of cancer and MSI in 8 types of cancer." (PMID 37388242, 2023). "Inversely, non-canonical NF-κB activation is dependent on activating IKKα to cause the formation of p52/RelB dimers in cancer cells." (PMID 35401542, 2022). "While it is well-established that RelB regulates MnSOD, little is known about the RelB partner that causes different responses in non-cancer cells versus PCa cells." (PMID 35742868, 2022). "Recently, RelB has been implicated in cancer progression, particularly in sex hormone-related cancers including BCa, prostate cancer (PCa) and cervical cancer." (PMID 32807176, 2020). "Although RELB, which causes cancer progression, significantly induced CCID formation the major role in this process was attributed to RELA/NFKB1 (“canonical” pathway)." (PMID 26513020, 2015). "Taken together, RelB was a promising prognostic marker for predicting cancer risk." (PMID 37388242, 2023). "Indeed, complex components IKKα, RelB and p52 are associated with decreased cancer-specific survival in ERa-positive breast cancer." (PMID 36034422, 2022). "However, when nuclear RelB was also present, the p65-dependent increase in risk was abolished (p = 0.344), supporting the hypothesis that RelB interferes with the cancer-related biological activity of p65." (PMID 26186215, 2015). "In contrast, AA-induced ROS in cancer cells downregulates RelB, reducing SIRT3 and MnSOD levels, thereby amplifying oxidative and metabolic stress in cancer cells." (PMID 40940976, 2025). "It has been demonstrated that EZH2 interacts with the NF-κB transcription factors, RelA and RelB, to activate pro-inflammatory genes in several cancer types, suggesting that the NF-κB target gene signature is positively regulated by EZH2." (PMID 39204206, 2024). "The results showed the promotor methylation level was significantly lower in cancer tissues, which implied RelB was an oncogenic role in pan-cancer." (PMID 37388242, 2023). "The result showed Vinorelbine was an effective inhibitor for RelB, and most cancers were sensitive to it." (PMID 37388242, 2023). "We observed RelB expression was positively correlated with the abundance of aDC, macrophages and monocytes in pan-cancer." (PMID 37388242, 2023). "The transcription factor NF-κB family, including p65 (RelA), RelB, c-Rel, p52, and p50, has crucial roles in innate immune response, inflammation, and cancer initiation and progression." (PMID 37111237, 2023). "RelB, a member of noncanonical NF-κB was abnormally regulated in most cancer types, however the molecular features and clinical signature of RelB expression, as well as its role in cancer immunity in human pan-cancer remains to be elucidated." (PMID 37388242, 2023). "We observed that higher expression of RelB was a risky threat in most cancer types but a protective factor in SARC, SKCM, BRCA." (PMID 37388242, 2023). "Since G9a and GLP play a role in inflammation in immune cells and cancer cells via interactions with members of the NF-κB family (p65, p50, and RelB), we investigated the possibility of a similar molecular mechanism occurring in adipocytes." (PMID 37237488, 2023). "Because RelB was a biomarker for cancer prognosis, we then investigated if there were any drugs that particularly targeted RelB in GDSC database." (PMID 37388242, 2023). "Kaplan-Meier analysis and Cox regression were used to explore the prognostic significance of RelB in human pan-cancer." (PMID 37388242, 2023).
cancer (continued). "In this study, we investigated the aberration expression and prognostic significance of RelB, and the correlation with clinicopathological characters and immune cells infiltration in various cancers." (PMID 37388242, 2023). "The relationship between RelB expression and clinic-pathological features in TCGA database was evaluated based on individual cancer stages." (PMID 37388242, 2023). "Our study was the first systematic analysis of RelB to verify its role in immune responses in pan-cancer." (PMID 37388242, 2023). "The pan-cancer patients were divided into two groups according to the median expression of RelB expression in various cancer types." (PMID 37388242, 2023). "The results showed that RelB was significantly upregulated from three aspects of gene, mRNA and protein respectively in various cancers, which was consistent with previous clinical trials and some basic studies." (PMID 37388242, 2023). "After coculture with activated T cells, the cancer cell survival rate fully recovered as RelB expression was restored." (PMID 35177112, 2022). "RT-PCR analysis demonstrated that BET and RT + BET treatments resulted in an increase in RELB mRNA in non-cancer cells but a decrease in PCa cells compared to vehicle treatment." (PMID 35742868, 2022). "In consideration of the putative role of RelB in the regulation of cancer immune escape, we examined the OncomineTM and TCGA datasets to enrich the potential relationship between PD-L1 and RelB signatures in cancer progression." (PMID 35177112, 2022). "The NF-κB family, comprised of five members: NF-κB1 (p50), NF-κB2 (p52), c-Rel, RelA (p65), and RelB, is a well-known transcription factor family which regulates a large number of target genes and plays crucial roles in cancers including GC." (PMID 35036435, 2022). "Accordingly, the numbers of active CD4+ and CD8+ T cells were apparently reduced by increasing RelB in the cancer cells." (PMID 35177112, 2022). "Treatment with BET resulted in an increase in the RelB-BLNK interaction in normal cells but a decrease in cancer cells, particularly in the nuclear fraction." (PMID 35742868, 2022). "Western blots confirmed an increase in RelB and MnSOD protein levels in non-cancer cells, PZ and PrEC, and a decrease in RelB and MnSOD protein levels in PC3 cells with BET ± RT treatments." (PMID 35742868, 2022). "We identified and verified that a steroid, betamethasone (BET), not only has all the required properties, but it also suppresses RelB expression in PCa cells and induces expression of RelB in non-cancer cells." (PMID 35742868, 2022). "NC-NFκB proteins (p52, RelB, and co-expression of p52/RelB) are nuclear proteins; they play a role in promoting cancer proliferation and progression." (PMID 34439182, 2021). "On this note, aberrant NF-κB signaling through both p65/p50 and RelB/p52 heterodimers correlates with cancer progression." (PMID 34198987, 2021). "BV6 also promotes the differentiation of GBM cancer stem-like cells in a RelB/p52-dependent manner, inducing the expression of CD133, Nanog, and Sox2 as well as GFAP." (PMID 34198987, 2021). "Since NF-κB directs pathways linking cancer with inflammation, we analyzed expression of transactivating NF-κB subunits c-Rel, RelB, and RelA in CSC-like cells." (PMID 33925297, 2021). "NC-NFκB proteins (p52, RelB, and co-expression of p52/RelB), which are nuclear proteins, plays a role in promoting cancer proliferation and progression." (PMID 34439182, 2021). "Upregulation of p50, p65 and c-Rel with increasing severity of lesion; immunoreactivity for p52, c-Rel and RelB in cancer tissues." (PMID 33344262, 2020). "We then examined if the induction of growth arrest upon PAK4 knockdown in cancer cells functionally involved RELB." (PMID 31399573, 2019). "LIGHT treatment readily results in accumulation of NIK, with concomitant increases in the levels of p52 and RelB, as well as one of p52 known targets in cancer cells, Cyclin D1." (PMID 30096845, 2018).